FGFR4 (fibroblast growth factor receptor 4)
Diseases named in the same sentence as FGFR4 in open-access papers (continued):
Sharing a sentence is not in itself a finding about the gene and the disease.
tumor (293 papers, 2003 to 2026). "Its rs351855 variant has been linked to tumor progression, therapy resistance, and poor prognosis, while FGFR4 overexpression is considered a marker of aggressive behavior in several malignancies." (PMID 40806692, 2025). "Given that FGFR4 activation has been linked to aggressive tumor phenotypes and therapeutic resistance, its higher prevalence in H/L patients raises important questions about its role in HCC progression and targeted therapy response." (PMID 40282485, 2025). "Similar to the SCAN-B and TCGA tumor cohorts, the DNA methylation status of the cg00618323 shore CpG was again strongly associated with FGFR4 expression levels in the cell line cohort (Wilcoxon’s p = 5e-05)." (PMID 40044693, 2025). "This aligns with research indicating that FGFR4 polymorphisms, particularly the FGFR4 p.Gly388Arg variant, negatively impact the prognosis of neoplastic diseases." (PMID 40776927, 2025). "Subsequent analysis of gene expression identified FGFR4 as the most significant eQTL of the risk allele rs353491-G in both myometrium (log-fold-change = 0.32, P = 0.008) and tumour RNA-seq (log-fold-change = 0.27, P = 0.004)." (PMID 40016412, 2025). "Increasing studies have implicated that FGFR4 is activated in most tumors and is involved in tumor growth, metastasis, and metabolism, acting as an oncogene." (PMID 39658878, 2024). "Suppression of the expression of FGFR4 and its ligand or impairment of their subsequent activation is considered to be a major cause of tumor growth." (PMID 38540215, 2024). "Significantly, DNA sequencing unveiled missense mutations in ABL, CCND3, CSF1R, KDR, and FGFR4, potentially contributing to tumor progression and angiogenesis in PF." (PMID 38732067, 2024). "Patients experiencing DC had more frequently a low tumour growth rate (P = 0.0306) and an FGFR4 p.G388R variant (P < 0.0001)." (PMID 38650006, 2024). "These mutations, which occur typically at amino acids 535 and 550 of the tyrosine kinase domain, cause FGFR4 to be constitutively active and drive tumor growth and metastasis." (PMID 37627061, 2023). "As expected, the IHC scores of Fgfr3 and Fgfr4 were decreased in Kdm6a‐deficient tumour tissues, confirming that FGFR3 and FGFR4 expression was positively associated with KDM6A expression." (PMID 37846441, 2023). "FGFR4 is also implicated in oncogenesis, tumor growth, and resistance to anti-tumor treatment in different types of cancer." (PMID 37415164, 2023). "EIF4A3 is consistently elevated in HCC patients and associated with tumour aggressiveness and mortality, through the modulation of FGFR4 splicing." (PMID 36419260, 2022). "Inherent level of circKCNN2 in HCC cells predisposes anti‐tumor effect of lenvatinib possibly because both circKCNN2 and lenvatinib repress the expression of FGFR4." (PMID 35051313, 2022). "At the experimental endpoint, loss of FGFR4 in HPAF-II cell line generated larger tumours with increased number of mitotic figures (and data not shown), and significantly increased the metastatic burden at the lungs and the liver." (PMID 35963908, 2022). "Validated in both intrinsic and acquired trastuzumab-resistant HER2-positive cell lines and cell-derived xenograft models, inhibition of FGFR4 dramatically increased cell and tumor susceptibility to anti-HER2 therapy." (PMID 35562334, 2022). "We noticed that only FGFR4 (cancer progression and tumor cell motility, OMIM ID: 134935) is classified as pathogenic in ClinVar." (PMID 36128740, 2022). "Inherent level of circKCNN2 in HCC cells predisposes anti‐tumor effect of lenvatinib possibly because circKCNN2 and lenvatinib repress the expression of FGFR4." (PMID 35051313, 2022). "Specifically, the FGFR4 Gly388 Arg polymorphism has been identified as a key mutation in the developing process of the tumor." (PMID 36547126, 2022). "At the endpoint, the tumour masses were significantly larger in animals transplanted with FGFR4 deficient cells." (PMID 35963908, 2022).
tumor (continued). "Instead, a single nucleotide polymorphism (SNP) at codon 388 of FGFR4 (rs351855), leading to a glycine to arginine conversion (G388R), has been connected to enhanced tumor susceptibility and aggressiveness in different tumor entities." (PMID 35484633, 2022). "FGFR4 SNP, rs351855, has been extensively reported for its association with the occurrence, progression, and prognosis of multiple tumor types." (PMID 34071523, 2021). "ADRM1 and FGFR4 were strongly correlated with tumor Stage, and ADRM1 was also associated with distant metastasis." (PMID 34724890, 2021). "Several genetic variants of FGFR4 have been shown to be associated with tumor progression in many cancers." (PMID 32781755, 2020). "In RMS, besides overexpression, FGFR4 has been shown to harbor activating mutations in over 6% of all tumors, resulting in constitutive tumor-promoting signaling within the cells." (PMID 33182650, 2020). "The polymorphism c.1162G>A; p.Gly388Arg of the Fgfr4 gene has been reported as pathogenic for cancer and tumor progression and is associated with a significant reduction in disease-free survival." (PMID 33231602, 2020). "Accumulating evidences also suggested that FGFR4-Arg388 allele was frequently seen in rapid tumor progression, increased metastasis and advanced stage of patients with breast, prostate, colon and lung cancer." (PMID 32154250, 2020). "Exon sequencing of 409 cancer-related genes identified enrichment of somatic mutations in FGFR3 and FGFR4 in the recurrent tumor compared with the treatment-naïve tumor, indicating a pivotal role for FGFR signaling in cancer cell survival through CIRT." (PMID 31540114, 2019). "Few studies have evaluated the relationship between the FGFR4 polymorphism and the tumor severity of UCC." (PMID 31878098, 2019). "Cancer progression and tumor cell motility were associated with the c.1162G > A (p.Gly388Arg) change in FGFR4 gene." (PMID 31207142, 2019). "Encouragingly, this study offers the advantages of the translational approach in mice and humans, and further effort is worthy and needed to study the FGF19/FGFR4 axis linked to tumor-initiation in human HCC." (PMID 29973237, 2018). "According to the in vitro results, we reported that FGFR4-388Gly overexpression in these xenografts caused decreased tumor growth in the H2009 cell line, and increased tumor growth in the H226 cell line, as compared to their respective control cell lines." (PMID 29402970, 2018). "Our results should be further confirmed in independent cohorts including a higher number of patients, and considering not only the FGFR4 variant present in the tumor, but also its expression level." (PMID 29402970, 2018). "A previous study found that high expression of the FGFR4 Arg388 allele was significantly associated with reduced overall survival and with an advanced tumor stage in HNSCC; data supporting our findings is available in the TCGA database." (PMID 29221201, 2017). "In cancers, aberrations of the FGFR4 genomic region include the amplification of FGFR4, activation of FGFR4 kinase domain mutations, and overexpression of FGFR4, which lead to sustained cell proliferation and contribute to tumor development." (PMID 29221201, 2017). "In IGC, only FGFR4 expression was significantly associated with factors relative to tumor progression and with shorter DSS (p = 0.012)." (PMID 28056982, 2017). "Cortisol has been shown to increase Fgfr4 expression, and this molecule has been specifically associated with extracellular matrix degradation and tumor invasion in prostate and other cancers." (PMID 28874141, 2017). "Unlike FGFR1-3, where activating mutations and genetic amplifications are commonly associated with tumor progression, FGFR4 is rarely mutated in human cancers." (PMID 27192118, 2016). "Fibroblast growth factor receptor 4 (FGFR4) polymorphisms are positively correlated with tumor progression in numerous malignant tumors." (PMID 25860955, 2015).
tumor (continued). "Several studies have shown that FGFR4 polymorphisms are associated with the progression of various tumor types, such as breast, colon, prostate, and sarcoma tumors." (PMID 26431494, 2015). "The FGFR4 gene SNP rs351855 (c.1162G>A, p.G388R), with a minor allele frequency of 0.3, is a predictor of progression and poor prognosis in a variety of human neoplasms." (PMID 26186299, 2015). "Amplification of other FGFRs has not been found in GC; however, overexpression of FGFR1 and FGFR4 or single nucleotide polymorphism of FGFR4 appears to be associated with tumor progression or survival." (PMID 26000013, 2015). "Consistent with the tumor-delaying effect of the FGFR4 deficiency, some of these changes largely have been associated with tumor development." (PMID 24279986, 2013). "Results indicate that mouse NAMPT is highly expressed in the luminal epithelium-derived tumor cells with highly expanded tubular, adenoid cystic and papillary tumor tissue structures (orange staining), and that FGFR4 deficiency attenuates the NAMPT levels." (PMID 24279986, 2013). "Here we showed that systemic and local metabolic alterations caused by a deficiency of the metabolic regulator FGFR4 reduce TGFα-induced tumor incidence and progression in breasts where FGFR4 expression is negligible." (PMID 24279986, 2013). "Multivariate analysis of the relationship between clinical and pathological tumor features with gene polymorphism and FGFR4 expression." (PMID 23226373, 2012). "Amplified FGFR4 signaling has been reported in head-and-neck squamous cell carcinoma, and has also been linked to accelerated tumor progression in breast and colon cancers." (PMID 22439738, 2012). "Epidemiological, clinical and pathological tumor features and their association with Gly388Arg polymorphism and FGFR4 expression." (PMID 23226373, 2012). "We plan to characterize the functional consequences of the two reported FGFR4 mutations and determine their prevalence in independent lung and other tumor specimen banks." (PMID 17487277, 2007). "Moreover, the FGF19/FGFR4 signaling pathway influences the polarization state of macrophages, promoting the M2 polarization of tumor-associated macrophages (TAMs)." (PMID 41328353, 2026). "In addition to CDK4 amplification, this patient’s tumor also harbored FGFR4 amplification, which has been associated with aggressive RMS behavior and therapeutic resistance." (PMID 40936693, 2025). "Additionally, a larger tumor diameter was associated with a higher likelihood of FGFR4 expression (median 12.0 mm vs 17.5 mm, p = 0.018), suggesting its contribution in tumor growth." (PMID 40393028, 2025). "Additionally, a larger tumor diameter was associated with a higher likelihood of FGFR4 expression (p = 0.018, effect size r = 0.247)." (PMID 40393028, 2025). "Recent studies have indicated that FGFR4 deficiency might regulate the tumor immune microenvironment by activating the antigen presentation process and cellular immunity to the change in sensitivity to immune checkpoint inhibitor treatment in NSCLC." (PMID 36142417, 2022). "Interestingly, the FGFR4-mutated RMS patient showed primary tumor in the abdominal wall, left orbital, and omentum." (PMID 34768995, 2021). "As a result, these findings suggest that the FGFR4 p.Gly388Arg allele may play a role in both aggressive tumor progression and tumor formation." (PMID 33456465, 2020). "In addition, FGFR4 overexpression is closely associated with advanced tumor stage and poor prognosis in astrocytomas." (PMID 32154250, 2020). "Therefore, our results uncover a clinically relevant, targetable mechanism of FGFR4 oncogenic activity via suppression of the stress-associated MST1/2-induced apoptosis machinery in tumor cells with prominent HER/ERBB and FGFR4 signaling-driven proliferation." (PMID 30903103, 2019). "However, in both cases, FGFR4-388Arg overexpression caused higher tumor growth, as compared to the rest of conditions." (PMID 29402970, 2018).
tumor (continued). "Aberrations of the fibroblast growth factor receptor 4 (FGFR4) genomic region include amplification of FGFR4, activation of FGFR4 kinase domain mutations, and overexpression of FGFR4, which lead to sustained cell proliferation and contribute to tumor development." (PMID 29221201, 2017). "Ponatinib treatment slows tumor growth in RMS mouse models expressing mutated FGFR4." (PMID 26420980, 2015). "Furthermore, ponatinib caused G1/S arrest of cell cycling and inhibition of in vivo tumor growth of RMS cells expressing the FGFR4 N535K and V550E mutations." (PMID 24124571, 2013). "We suggest that the tumor-delaying effect of FGFR4 deficiency may be in large part due to elevated anti-obesogenic FGF21 that triggers tumor-suppressing signals from both peripheral and breast adipocytes." (PMID 24279986, 2013). "These activities of FGF21 and possibly FGF19 on adipocytes that elicit tumor suppressive metabolic signals appear sufficient to override tumor-promoting effects of elevated bile acids, inflammation and mild metabolic abnormalities elicited by the FGFR4 deficiency." (PMID 24279986, 2013). "However, the classification standard of Gleason score was not uniform; thus, we only focused on the association between FGFR4 Gly388Arg polymorphism and tumor stage (advanced vs. localized)." (PMID 21349172, 2011). "Similarly, loss of Sef was observed in 44% of tumours with weak or moderate FGFR4 expression and also in 41% of tumours with strong FGFR4 expression (P=0.81)." (PMID 19888221, 2009). "Recently, a common polymorphism in the transmembrane domain of the FGFR4 gene, Gly388Arg, has been reported to correlate with tumour aggressiveness (lymph node metastasis, advanced stage at presentation and reduced survival in several cancer types, including breast, sarcoma, lung and prostate)." (PMID 17519899, 2007). "However, there was a strong correlation between the presence of at least one FGFR4 Arg388 allele and tumour thickness according to Clark's level of invasion IV and V as opposed to I, II and III (P=0.004) and to Breslow's thickness (⩽1 mm vs >1 mm; P=0.02)." (PMID 16721364, 2006). "Our data lead to the conclusion that FGFR4 protein expression is linked with tumour progression." (PMID 16721364, 2006). "The metabolic reprogramming of breast epithelial cells caused by these changes contributes to the suppression of tumor progression, suggesting that the tumor-delaying effect of FGFR4 deficiency may be largely attributed to the elevated anti-obesogenic FGF21 and its resultant metabolic effects." (PMID 41328353, 2026). "FGFR4 activation has been associated with cancer progression and resistance to different types of anti-cancer therapy and preclinical studies have shown that FGFR4 knockdown or pharmacologic inhibition can inhibit tumor growth and metastasis both in vitro and in vivo (see58 for review)." (PMID 40044693, 2025). "Moreover, the expression of tyrosine kinase FGFR4 was associated with the proliferative characteristic of PT and could be a marker for more aggressive tumour behaviour." (PMID 38187082, 2023). "Therefore, for RMS without FGFR4 activating mutations, rather than through suppressing its kinase activity, targeting FGFR4 as a tumor-associated antigen (TAA) using immunotherapy may be more effective." (PMID 37627061, 2023). "Our findings provide novel mechanistic insight into tumor aggressiveness that is associated with MT-mediated upregulation of FGF19/FGFR4 signaling axis, suggesting that inactivating this molecular node may help actualize the promise of MT supplements in cancers." (PMID 33691750, 2021). "Therefore we propose that a simultaneous increase of FGF19/FGFR4 associated with an increased level of EpCAM may help to identify which patients may have a more aggressive and resistant tumor biology requiring multi-drug therapy." (PMID 27447573, 2016). "Finally, ponatinib treatment inhibited tumor growth in a RMS mouse model expressing mutated FGFR4." (PMID 24124571, 2013).
tumor (continued). "In addition, the FGFR4 Arg388 allele may predispose cancer patients to disease progression, based on the reported significant association between FGFR4 genotype and tumor aggressiveness or patients' survival in several cancers." (PMID 21349172, 2011). "FGF19 exerts a significant impact on promoting tumor cell proliferation primarily through the activation of the FGFR4 signaling pathway." (PMID 41328353, 2026). "In particular, the FGFR4.28HTM.28z-CD276.8HTM.BBz BiCisCAR T cells have demonstrated faster tumor clearance, higher persistence, and lower expression of exhaustion markers in RMS models." (PMID 41328353, 2026). "In preclinical experiments, HS236 demonstrated significant inhibitory effects on the proliferation of FGF19-positive tumor cells in vitro by selectively binding to the FGFR4 target in tumor cells and blocking its function." (PMID 41328353, 2026). "In the context of HCC, FGF19, the ligand for FGFR4, is frequently amplified and overexpressed, leading to the activation of the FGFR4 signalling pathway and contributing to tumour development and progression." (PMID 41503573, 2026). "Through the activation of downstream MAPK and PI3K/AKT pathways via its receptor FGFR4, mTORC1 activity is enhanced, thereby promoting amino acid uptake and utilization, processes that are essential for rapid tumor cell proliferation." (PMID 41328353, 2026). "In BC research, transfection with specific siRNA to silence the FGF19 gene can effectively block the signaling between FGF19 and FGFR4, inhibiting the proliferation and migration of tumor cells." (PMID 41328353, 2026). "FGF19 overexpression is often observed in various cancers, and its contribution to tumor progression is primarily mediated through the activation of FGFR4, although the specific mechanisms and outcomes differ among cancer types." (PMID 41328353, 2026). "Two preclinical CAR-T constructs, RJ154-HL and 3A11, utilizing distinct single-chain variable fragments (scFvs) specific for FGFR4, have demonstrated potent anti-tumor activity." (PMID 41584352, 2026). "This combined therapy works by inhibiting the FGFR2/3 and FGF19/FGFR4 signaling pathways, thereby curbing tumor cell proliferation and inducing apoptosis." (PMID 41328353, 2026). "The experiments showed that the KLB knockout had a stronger inhibitory effect on cell growth and tumor growth than the FGFR4 knockout." (PMID 41328353, 2026). "The 3A11 CAR-T cells have demonstrated robust cytokine secretion and cytotoxicity against RMS cell lines in vitro, without recognition and killing of healthy human primary cells, confirming their selectivity for tumor cells with high FGFR4 expression." (PMID 41328353, 2026). "Compared with those in CT-26/EV cells, CT-26/FGFR4 tumor-derived CAFs exhibited higher expression levels of CAF markers, such as α-SMA, fibroblast activation protein (FAP), PDGF receptor (PDGFR), and vimentin, at both mRNA and protein levels." (PMID 40447617, 2025). "We also found that FGFR4 and related metabolic genes (SLC2A1, LDHA, PFKL) were upregulated in tumors and FGFR4 high-expression groups, suggesting FGFR4's role in tumor metabolism." (PMID 40091020, 2025). "The crosstalk between the tumor microenvironment and the FGFR4-positive tumor cells merits further investigation." (PMID 41213916, 2025). "In CRC, our study confirms that FGFR4 is highly upregulated in tumor cells, consistent with prior data correlating FGFR4 expression with poor prognosis." (PMID 41210688, 2025). "FGFR4 exhibited differential expression across tumor types and was most highly expressed in PR-Negative, ER-Indeterminate, HER2-Positive, and PAM50 Her2 subtypes." (PMID 40091020, 2025). "FGFR4-directed agents show activity in FGF19-positive tumours, yet resistance mechanisms argue for refined biomarkers and rational combinations." (PMID 41301037, 2025).